MT-TG (mitochondrially encoded tRNA-Gly (GGN))
Synonyms: trnG; formerly MTTG
Gene: Mitochondrial transfer RNA gene on chromosome MT (9,991 to 10,058, forward strand). Ensembl gene ENSG00000210164.
Gene-disease validity (ClinGen):
ClinGen rates the evidence that MT-TG causes each of these diseases.
mitochondrial disease (mitochondrial): Moderate.
Diseases named in the same sentence as MT-TG in open-access papers:
MT-TG is named in the same sentence as 1 disease in open-access papers, as found by Europe PMC text mining. Sharing a sentence is not in itself a finding about the gene and the disease. The quoted sentences say what the papers report.
diabetes (1 paper, 2015). "The underlying mechanism by which MT-tg impairs pancreatic β-cell function and induces diabetes is not clear; however, the present study and other related reports may provide some clues." (PMID 26335571, 2015). "MT-tg overexpression significantly protected mice from acute STZ-induced ROS at 8 weeks of age; unexpectedly, however, MT-tg impaired glucose stimulated insulin secretion (GSIS) and promoted the development of diabetes." (PMID 26335571, 2015).